TRBV5-1 (T cell receptor beta variable 5-1)
Description:
V region of the variable domain of T cell receptor (TR) beta chain that participates in the antigen recognition. Alpha-beta T cell receptors are antigen specific receptors which are essential to the immune response and are present on the cell surface of T lymphocytes. Recognize peptide-major histocompatibility (MH) (pMH) complexes that are displayed by antigen presenting cells (APC), a prerequisite for efficient T cell adaptive immunity against pathogens. Binding of alpha-beta TR to pMH complex initiates TR-CD3 clustering on the cell surface and intracellular activation of LCK that phosphorylates the ITAM motifs of CD3G, CD3D, CD3E and CD247 enabling the recruitment of ZAP70. In turn ZAP70 phosphorylates LAT, which recruits numerous signaling molecules to form the LAT signalosome. The LAT signalosome propagates signal branching to three major signaling pathways, the calcium, the mitogen-activated protein kinase (MAPK) kinase and the nuclear factor NF-kappa-B (NF-kB) pathways, leading to the mobilization of transcription factors that are critical for gene expression and essential for T cell growth and differentiation. The T cell repertoire is generated in the thymus, by V-(D)-J rearrangement. This repertoire is then shaped by intrathymic selection events to generate a peripheral T cell pool of self-MH restricted, non-autoaggressive T cells. Post-thymic interaction of alpha-beta TR with the pMH complexes shapes TR structural and functional avidity.
Synonyms: TCRBV5S1A1T; TRBV51; TCRBV5S1
Tractability: Antibody: UniProt places it where antibodies can reach, with medium confidence; UniProt predicts a signal peptide or a membrane-spanning region; its Gene Ontology location is reachable by antibodies, with medium confidence.
Gene: T-cell receptor variable (V) gene on chromosome 7 (142,320,677 to 142,321,544, forward strand). Ensembl gene ENSG00000211734.
Subcellular location: Cell membrane
Gene Ontology:
Biological process: cell surface receptor signaling pathway
Cellular component: plasma membrane
Homologues: Orthologues: macaque TRBV5-1 (89% identical). Paralogues in human: TRBV5-3 (77% identical), TRBV5-5 (75% identical), TRBV5-6 (72% identical), TRBV5-7 (70% identical), TRBV5-4 (69% identical), TRBV9 (63% identical), TRBV13 (59% identical), TRBV7-4 (49% identical), TRBV7-9 (49% identical), TRBV7-6 (48% identical), TRBV7-7 (48% identical), TRBV11-3 (47% identical), and 39 more.
Diseases named in the same sentence as TRBV5-1 in open-access papers:
TRBV5-1 is named in the same sentence as 4 diseases in open-access papers, as found by Europe PMC text mining. Sharing a sentence is not in itself a finding about the gene and the disease. The quoted sentences say what the papers report.
contact dermatitis (1 paper, 2021). An inflammatory skin condition caused by direct contact between the skin and either an irritating substance or an allergen. "In this study, we showed several highly expanded T cell clones by sequencing data, and demonstrated the preferential usage of TRBV19, TRBV5-1, and TRBV20-1, consistent with previous studies on Ni2+ contact dermatitis." (PMID 33670995, 2021).
T-cell neoplasms (1 paper, 2024). "This approach offers a promising pathway for patients with mature T-cell neoplasms where TRBV5-1 expression is a defining feature." (PMID 39742266, 2024).
infection (1 paper, 2025). The state of being infected such as from the introduction of a foreign agent such as serum, vaccine, antigenic substance or organism. "Several common TRA and TRB pairs, such as TRAV1-2/TRAJ33, TRAV21/TRAJ49, TRBV6-4/TRBD2/TRBJ2-3, and TRBV5-1/TRBD1/TRBJ2-7, were consistently detected from the primary infection (PI) through the convalescent phase (HC) and into the reinfection phase (RI)." (PMID 41209021, 2025).
tumor (1 paper, 2024). "Flow cytometry analysis on patients’ samples demonstrated that the antibody, conjugated with a fluorochrome, selectively binds to tumor T lymphocytes expressing TRBV5-1, without binding to other lymphocytes or blood cell components." (PMID 39742266, 2024).